MIR489 (microRNA 489)
Synonyms: hsa-mir-489; MIRN489; mir-489
Gene: MicroRNA gene on chromosome 7 (93,483,936 to 93,484,019, reverse strand). Ensembl gene ENSG00000207656.
Gene Ontology:
Biological process: miRNA-mediated post-transcriptional gene silencing
Cellular component: RISC complex
Homologues: Orthologues: chimpanzee ptr-mir-489 (100% identical), macaque mml-mir-489 (98% identical), dog MIR489 (96% identical), pig ssc-mir-489 (89% identical), tropical clawed frog xtr-mir-489 (85% identical), zebrafish mir489 (75% identical), mouse Mir489 (70% identical), rabbit MIR489 (64% identical).